SKP2 (S-phase kinase associated protein 2)
Diseases named in the same sentence as SKP2 in open-access papers (continued):
Sharing a sentence is not in itself a finding about the gene and the disease.
breast carcinoma (continued). "Other notable breast cancer related genes identified by super-delta include YBX1, KPNA2, SKP2, and NAT1." (PMID 29268715, 2017). "FOXP3 has been reported as a suppressor gene in breast cancer and prostate cancer via repressing the expression of oncogene such as HER2, SKP2, p21, LATS2 and c-Myc." (PMID 28716029, 2017). "In breast cancer, the FOXP3 has been described as a transcriptional repressor of genes involved in tumor development, like HER2 and SKP2, and also in cancer progression, like CXCR4." (PMID 27830498, 2016). "Conversely, TLK2 inhibition selectively inhibits the growth of TLK2-high breast cancer cells, downregulates ERα, BCL2 and SKP2, impairs G1/S cell cycle progression, induces apoptosis and significantly improves progression-free survival in vivo." (PMID 27694828, 2016). "Therefore, inhibition of Skp2 could be a promising approach for treating breast cancer." (PMID 27582552, 2016). "More importantly, the inverse correlation between Skp2 and SIRT3 immunohistochemical staining was observed in breast cancer tissues." (PMID 23230084, 2012). "For example, it has been found that NONO can regulate the proliferation of breast cancer cells by affecting the expression of SKP2 and E2F8." (PMID 40826746, 2025). "In breast cancer, NONO promotes cell proliferation by regulating the post-transcriptional expression of S-phase kinase-associated protein 2 (SKP2) and the Elongation Factor (E2F) transcription factor." (PMID 40943463, 2025). "SKPin C1 has also been reported to inhibit uveal melanoma and lung cancer growth both in vitro and in vivo; trigger cell apoptosis in metastatic melanoma and breast cancer in vitro; and inhibit proliferation of murine primary T-ALL cells with wildtype Skp2, as well as several human T-ALL cell lines." (PMID 37089937, 2023). "Mechanistically, TRIB3 can facilitate breast cancer stem cells through regulating AKT to interfere with the FOXO1-AKT interaction and inhibit FOXO1 phosphorylation, ubiquitination, and degradation by E3 ligases SKP2 and NEDD4L." (PMID 37732314, 2023). "The RBP NONO plays an oncogenic role in breast cancer and modifies SKP2 and E2F8 in the post‐transcriptional phase." (PMID 34890108, 2022). "Similarly, stress and EGF induced Akt activation and promoted breast cancer progression, which developed drug resistance through AMPK-mediated Skp2 phosphorylation in this process." (PMID 34829834, 2021). "Breast cancer patients with high expression of both USP18 and Skp2 had the worst survival rates, which suggested that USP18/Skp2 may act as a potential biomarker in breast cancer." (PMID 34068643, 2021). "FOXP3 expression is not restricted to the lymphocyte lineage, but it is also present in some cancer cells, especially in breast cancer cells, where it has been demonstrated to be a cancer-suppressor gene and an important regulator of the HER2/ErbB2 and SKP2 oncogenes." (PMID 33671179, 2021). "FOXP3 may behave as a transcriptional repressor of SKP2 and HER2, acting as a potential tumor-suppressor gene in breast cancer, prostate, gastric cancer, or hepatocellular carcinoma." (PMID 33671179, 2021). "In response to DNA damage, SKP2 enhances phosphorylation and ubiquitination of programmed cell death protein 4 (PDCD4) to inhibit apoptosis with subsequent increase in cell growth and proliferation of breast cancer cells." (PMID 32226545, 2020). "A Skp2-mH2A1-CDK8 axis may be key to regulation of the G2/M transition, polyploidy, cell proliferation, and cell migration, and thus in the development of breast cancer." (PMID 31248103, 2019). "SKP2 was upregulated and PDCD4 was downregulated in breast cancer samples." (PMID 30760284, 2019). "Thus, to further investigate the molecular mechanism by which of β-lap inhibited breast cancer cell proliferation, DEK and Skp2 expression were detected in MCF-7 and MDA-MB-231 cells following β-lap treatment." (PMID 28578385, 2017).
breast carcinoma (continued). "In addition to SKP2, the FKHR family transcription factors (FOXO) have also been reported to be downstream targets of Akt that mediate apoptosis in breast cancer." (PMID 25530715, 2014). "The aims of this study is to examine the concentration- and time-related effects of curcumin on two different breast cancer cells, MCF-7 and MDA-MB-231, and investigated the functional changes induced by curcumin treatment, as well as their relationship to the PI3K/Akt-SKP2-Cip/Kips pathway." (PMID 25530715, 2014). "The subset of Skp2 positive / ER negative breast carcinomas were also characterized by high tumor grade and HER2 negative." (PMID 23497154, 2013). "Expression of the genes in the PLK1-MCM complex-SKP2 subnet of breast cancer patient datasets is up regulated in ER negative samples; expression of the genes in the PLK1-MCM complex-SKP2 subnet of NSCLC patient dataset is up regulated in lung cancer samples." (PMID 22838965, 2012). "An inverse correlation between Skp2 expression and the expression of ER and PGR has been reported by others investigating breast cancer and other studies suggest that Skp2B may modulate the activity of the estrogen receptor." (PMID 23071715, 2012). "In contrast, analysis of the clinicopathological significance of nuclear Skp2 expression in patients with breast carcinoma revealed no statistical significance between nuclear Skp2 expression and clinicopathological factors." (PMID 23300741, 2012). "David functional annotation analysis showed 75% genes of the PLK1-MCM complex-SKP2 subnet in breast cancer patient datasets and 70.7% genes of the PLK1-MCM complex-SKP2 subnet in NSCLC patient datasets are involved in the Reactome pathway of “Cell Cycle, Mitotic”." (PMID 22838965, 2012). "To examine whether this association was valid in other cell lines, we examined the effect of rapamycin on cell proliferation and Skp2 expression in MDA-MB-231, a breast cancer cell line that has shown delayed sensitivity to rapamycin." (PMID 16859513, 2006). "The fact that CD24 is an important driver of cell proliferation in many types of cancer, including breast cancer, is consistent with its correlation with Ki-67, SKP2 expression, and the lack of p21 and p27 cell cycle checkpoints expression that we observed in our breast cancer samples." (PMID 40943144, 2025). "Finally, immunohistochemistry in 74 breast cancer patients confirmed PD-L1 and SKP-p21/p27 axis relationship, as it showed a highly statistically significant correlation between SKP2 and PD-L1 expression (p < 0.001), and both correlated significantly with the proliferation marker Ki-67 (p < 0.001)." (PMID 38725021, 2024). "However, in breast cancer cell lines MCF-7 and MDA-MB-231, pancreatic cancer cell lines Patu8988 and Panc1, rottlerin treatment inhibits tumor cell proliferation, migration and invasion, which is due to downregulated Skp2 expression at mRNA and protein levels." (PMID 37089937, 2023). "Moreover, AMPK-mediated Skp2 S256 and AKT S473 phosphorylation promotes breast cancer progression in mouse tumor models and significantly correlates with metastasis-free survival in breast cancer patients." (PMID 38102722, 2023). "Skp2 inhibits apoptosis by inducing the polyubiquitination and degradation of FOXO1 in prostate cancer and induces the phosphorylation and ubiquitin-mediated degradation of PDCD4 in breast cancer to suppress apoptosis and increase cell proliferation and radiotherapy resistance." (PMID 36552825, 2022). "It is also reported that Skp2 can be phosphorylated on Ser64 by p38/MAPK, protecting Skp2 from proteasomal degradation by NK3 homeobox 1 (Nkx3-1), finally leading to Oct-4 (Octamer-binding transcription factor) over-expression and contributing to tamoxifen-resistance in MCF-7 breast cancer cells." (PMID 34068643, 2021).
breast carcinoma (continued). "Additionally, Skp2 knockdown suppressed glucose uptake and glycolysis by reduced Glu1 transcription and protein expression in breast cancer cells upon EGF or HRG stimulation, repressing breast cancer development." (PMID 34068643, 2021). "Moreover, overexpression of Skp2 or Skp2 S256D, but not Skp2 S256A, promoted breast cancer development." (PMID 30413706, 2018). "To estimate whether the highly penetrant Rb/SKP2 synthetic lethality in TNBC extended to other cancer histologies, we re-analysed the results of two recent large-scale shRNA screens that encompass TCLs derived from non-breast cancer histologies." (PMID 29915391, 2018). "Therefore, the downregulation of Skp2 expression may also contribute to the FKA induced G2M arrest and cell growth inhibition in HER2-overexpressing breast cancer." (PMID 28335434, 2017). "Given that, in a subset of breast cancers (32 out of 84 samples), p27 levels were low despite SKP2 not being expressed, it remains possible that the expression of KPC might be elevated in such cases." (PMID 27542266, 2016). "In various tumor models, the absence of Skp2 impairs AKT activation, Glut1 expression, glucose uptake, glycolysis, and the progression of breast cancer." (PMID 39769140, 2024). "SKP2 and PDCD4 showed negative correlation in human breast cancer tissues." (PMID 30760284, 2019). "Our group has previously shown that overexpression of PPARγ can down-regulate Skp2 expression in MDA-MB-231 breast tumor cells, but whether or not Skp2 influences PPARγ function in breast cancer has not yet been determined." (PMID 23939428, 2013).
prostate carcinoma (90 papers, 2009 to 2026). A carcinoma that arises from epithelial cells of the prostate gland. "Overexpression of SKP2 is frequently observed and associated with cancer progression, metastasis, and poor prognosis in a wide variety of cancers including prostate cancer." (PMID 41542047, 2026). "SKP2 is also associated with the acquired drug resistance like paclitaxel resistance in prostate cancer." (PMID 41542047, 2026). "We analyzed expressions of known p27-targeting E3 ubiquitin ligases, such as CUL1 (cullin 1), SKP1 (S-phase kinase associated-protein 1), and SKP2, in prostate cancer cells." (PMID 40251202, 2025). "SKP2 knockdown inhibits EZH2 expression prostate cancer cells by promoting TRAF6-induced K63-linked ubiquitination of EZH2 for degradation." (PMID 36202787, 2022). "Although Skp2 has previously been associated with a mesenchymal phenotype and prostate cancer progression, the relationship with Slug deserves further elucidation." (PMID 33799604, 2021). "Conversely, low CD24 expression is linked to the mesenchymal phenotype of metastatic prostate cancer cells that have characteristics of cancer stem-like cells associated with high Skp2 expression." (PMID 30952903, 2019). "High Skp2 expression is further associated with the mesenchymal phenotype in prostate cancer patients and in vitro." (PMID 30952903, 2019). "Lastly, we showed an inverse relationship between Skp2 expression and CD44+CD24− cancer stem-like subpopulation, suggesting that Skp2 is a promising marker for prostate cancer susceptibility." (PMID 30952903, 2019). "Defects in the RB1 tumour suppressor are one of the more common driver alterations in prostate cancer progression and Skp2 was shown to be required for RB1 loss initiated pituitary tumorigenesis." (PMID 30885218, 2019). "As a result of SKP2 overexpression, LNCaP-SKP2 cells exhibited downregulation of the cyclin-dependent kinase inhibitor p27, a hallmark of aggressive prostate cancer." (PMID 29861853, 2018). "For example, S-phase kinase associated protein-2 (SKP2) was shown to increase the level of H3K4me3 through decreasing the K63-linked ubiquitination of KDM5B by E3 ubiquitin ligase TRAF6 in prostate cancer cells." (PMID 27974677, 2017). "Since either mutated or silenced Pten and Rb are common in prostate cancer, Skp2 represents an appealing drug target for prostate cancer prevention and therapy." (PMID 26497688, 2015). "Skp2 overexpression in prostate cancer is positively associated with Gleason score, tumor grade, and biochemical failure in men treated by prostatectomy." (PMID 26497688, 2015). "S-phase-associated kinase protein-2 (Skp2) is a member of Skp, Cullin, F-box containing complex that functions as an ubiquitin E3 ligase, which is significantly elevated in prostate cancer." (PMID 25115390, 2014). "In addition, to develop prostate cancer immunoprevention and immunotherapy approaches by targeting human SKP2 oncogene and its associate pathways, a prostate-specific SKP2 humanized mouse model is critical." (PMID 41542047, 2026). "Our analysis of publicly available datasets shows that SKP2 gene is frequently amplified in multiple cancers, including sarcoma, urothelial cancer, and prostate cancer, and that higher SKP2 mRNA levels in prostate tumor tissues are associated with poorer overall survival of prostate cancer patients." (PMID 41542047, 2026). "The stability of Twist is promoted via its K63-linked ubiquitination by SKP2 in prostate cancer." (PMID 32826949, 2020). "The second is the Skp2 (S-phase kinase-associated protein 2) /SCF complex in prostate cancer." (PMID 33096593, 2020). "Notably, an over-expression of Skp2 in prostate cancer tissue has been reported to be associated with a low level of p27, higher Gleason score, more advanced pathological stage, higher Ki-67 index, and poor prognosis." (PMID 26416244, 2015).
prostate carcinoma (continued). "Since triol treatment caused a significant decrease in Skp2 expression and an increase in p27Kip expression in all three prostate cancer cell lines, we next wished to determine if overexpression of Skp2 would block the growth inhibition caused by triol in PC-3 cells." (PMID 23785446, 2013). "Furthermore, transgenic expression of SKP2 in the mouse prostate causes low-grade prostate carcinomas that coincide with p27 downregulation." (PMID 21182779, 2010). "Similarly, accentuated Skp2 expression in prostate carcinomas may result in the loss of the tumor suppressor gene BRCA2." (PMID 23087899, 2012). "We have previously reported that FKA acts as a SKP2 degrader for selectively inhibiting the growth of prostate cancer PC3 cells overexpressing SKP2." (PMID 41542047, 2026). "We also show that SKP2 overexpression in prostate cancer PC3 cells increases the protein levels of TWIST1 and the expression of EMT related genes, including FMOD, THY1, NFIL3 and IRF2, leading to a marked increase in migration and invasion." (PMID 41542047, 2026). "Skp2 promotes G1/S phase conversion by degrading p27 (cell cycle inhibitor), and its overexpression is related to the aggressiveness of lung and prostate cancer." (PMID 40534867, 2025). "In the study, SKP2 modulated H3K4me3 levels by regulating TRAF6-mediated K63-linked ubiquitination of JARID1B, a key demethylase of H3K4me3, thereby influencing prostate cancer migration and recurrence." (PMID 40771930, 2025). "In prostate cancer cells, this mutant showed reduced binding to SKP2 and decreased SKP2-mediated ubiquitination of GSDME." (PMID 41413917, 2025). "In prostate cancer, high expression of SKP2 leads to IDH1 degradation, enhances glycolysis and promotes tumor proliferation." (PMID 40534867, 2025). "Concurrently, assessing the ubiquitination levels of ACSL4 in prostate cancer cells, we ascertained that SKP2’s overexpression markedly amplified ACSL4 ubiquitination in a dose-correlated manner." (PMID 39261475, 2024). "TRIM33 was recently reported to have stabilizing effects on androgen receptors in prostate cancer cells by preventing Skp-2 mediated proteasomal degradation." (PMID 38473207, 2024). "Genetic and pharmacological inactivation of SKP2 has been shown to reduce the CSC population in prostate cancer." (PMID 38355807, 2024). "It has been reported that increased SKP2 expression following the adhesion of prostate cancer cells to basement membranes leads to the degradation of BRCA2 and promotes cell proliferation." (PMID 39062881, 2024). "Another report found that crocin suppresses the re-proliferation of quiescent prostate cancer cells in vitro via down-regulation of important regulatory transcription factors such as Skp2, E2F1, NF-kB, C-myc, and other cell-cycle-regulatory genes." (PMID 38201944, 2023). "It has been reported to be a cell-active ubiquitination inhibitor in prostate cancer that selectively degrades Skp2 and upregulates FBXW2 expression, thus inducing autophagy and inhibiting cancer cell growth." (PMID 37089937, 2023). "Compound SMIP0004 has been found to restrain Skp2 expression, thus protecting p27 from degradation to induce p27 accumulation, finally inhibiting prostate cancer cell growth and inducing apoptosis." (PMID 37532777, 2023). "It is detected that the protein level of SKP2 is upregulated in various types of human cancers containing liver cancer, lymphoma, and prostate cancer." (PMID 35401213, 2022). "With inhibition of the neddylation of Cullin1 and Ubc12, flavokawain A (FKA), flavokawain B (FKB), and gartanin induced Skp2 degradation, which inhibited cell growth and induced autophagy in prostate cancer." (PMID 34068643, 2021).